NCF1C (neutrophil cytosolic factor 1C (pseudogene))
Description:
May be required for activation of the latent NADPH oxidase (necessary for superoxide production).
Synonyms: SH3PXD1C
Gene: Transcribed unprocessed pseudogene on chromosome 7 (75,156,639 to 75,172,044, reverse strand). Ensembl gene ENSG00000165178.
Subcellular location: Cytoplasm
Diseases named in the same sentence as NCF1C in open-access papers:
NCF1C is named in the same sentence as 12 diseases in open-access papers, as found by Europe PMC text mining. Sharing a sentence is not in itself a finding about the gene and the disease. The quoted sentences say what the papers report.
sarcoma (2 papers, 2021 to 2022). A usually aggressive malignant neoplasm of the soft tissue or bone. "One bioinformatic analysis reported that the overexpression of the lncRNAs ADAM6, C5orf58, CXCR2P1, FCGR2C, HCP5, HLA-H, NAPSB, NCF1B, and NCF1C reduced the sensitivity of sarcoma to ICIs." (PMID 36326232, 2022). "The expression of nine ICLs, ADAM6, C5orf58, CXCR2P1, FCGR2C, HCP5, HLA-H, NAPSB, NCF1B and NCF1C, was further investigated in different cancer types, including sarcoma." (PMID 34178688, 2021). "For C5orf58, HLA-H and NCF1C, a negative correlation of the expression of ICLs and DNA methylation was observed in sarcoma." (PMID 34178688, 2021).
bladder cancer (1 paper, 2022). "Several lncRNAs such as NCF1C, NCF1B, CXCR2P1, LINC02446, and AC0048473.1 have a high number of target genes that are associated with immune function, indicating that these lncRNAs are functionally related to immune activation in bladder cancer." (PMID 36091015, 2022).
chronic granulomatous disease (1 paper, 2022). Chronic granulomatous disease (CGD) is a rare primary immunodeficiency, mainly affecting phagocytes, which is characterized by an increased susceptibility to severe and recurrent bacterial and fungal infections, along with the development of granulomas. "For example, chronic granulomatous disease (CGD) is caused by the chimeric form of NCF1 (neutrophil cytosolic factor 1) and its pseudogenes NCF1B (neutrophil cytosolic factor 1B pseudogene) and NCF1C (neutrophil cytosolic factor 1C pseudogene)." (PMID 35012455, 2022).
latent infection (1 paper, 2021). "This may imply that the expression of NCF1C may protect the close contacts of active leprosy patients from being infected with M. leprae, which may serve as a potential biomarker of latent infection with M. leprae." (PMID 34993156, 2021).
leprosy (1 paper, 2021). Leprosy is a chronic infectious disease affecting primarily the skin and peripheral nervous system. "Our study has shown that the expression of NCF1C was 3.4-fold higher among household healthy controls than that of leprosy patients." (PMID 34993156, 2021). "In sum, IL-8, CCL2, SERP, and NCF1C showed an excellent performance in distinguishing leprosy patients from healthy controls." (PMID 34993156, 2021). "In addition, LOC34487, LOC101928143, CCL2, and NCF1C had the potential to distinguish MB and PB leprosy patients from HHCs." (PMID 34993156, 2021). "The results showed that the decreased expression of NCF1C among leprosy patients had the highest performance that could discriminate leprosy patients from HHCs." (PMID 34993156, 2021). "Moreover, we found decreased expression of NCF1C among leprosy patients could distinguish leprosy from HHCs, whereas higher expression of CCL2 among MB than PB could distinguish different leprosy patients." (PMID 34993156, 2021).
pancreatic cancer (1 paper, 2020). "Only 3 pseudogenes (NAMPTP1 NCF1B NCF1C) were remarkably upregulated in pancreatic cancer samples compared to normal controls." (PMID 33027767, 2020).
tuberculosis (1 paper, 2021). A chronic, recurrent infection caused by the bacterium Mycobacterium tuberculosis. "A recent study from England and India indicated NCF1C can be an immune biomarker to differentiate active tuberculosis and latent tuberculosis." (PMID 34993156, 2021).
cancer (3 papers, 2020 to 2022). A tumor composed of atypical neoplastic, often pleomorphic cells that invade other tissues. "Using GEPIA database, three (NAMPTP1 NCF1B NCF1C) out of 92 predicted pseudogenes were found to be remarkably upregulated in cancer samples." (PMID 33027767, 2020). "However, for the remaining pseudogenes (DDX12P, NCF1C, RP9P, and YWHAZP4), there were no reports on their biological functions in cancers." (PMID 36272991, 2022).
tumor (3 papers, 2019 to 2022). "Heatmap indicated that NCF1C, HLA-DRB6, HLA-DPB2, HLA-J, HLA-H, HLA-L and RPL13AP20 displayed high expressions in the low-risk group, and thus were categorized as tumor-suppressor pseudogenes in the current study." (PMID 33378744, 2020). "Except for GVINP1 and NCF1C, the expression of the other 5 prognosis-related DE pseudogenes (DDX12P, FER1L4, NSUN5P2, PLEKHA8P1 and RP9P) were higher in tumor tissues than in cutting edge normal tissues, which was totally consistent with the results of TCGA samples." (PMID 36272991, 2022).
NCF1C also shares sentences with these, for which no sentence is quoted: astrocytoma (1 paper); breast carcinoma (1); scleroderma (1).